CXCL13 (C-X-C motif chemokine ligand 13)
Diseases named in the same sentence as CXCL13 in open-access papers (continued):
Sharing a sentence is not in itself a finding about the gene and the disease.
tumor (continued). "To further validate the positive relationship between the CD74‐202/CD74‐201 ratio and the enrichment of CD8+CXCL13+ Tex cells and C1QC+ TAMs, we performed the same SiT sequencing and analysis pipeline on 13 tumor samples extracted from 13 ESCC patients." (PMID 39312471, 2024). "Classically, CXCL13 coordinates B cells, which in combination with CXCL13 producing CD4+ T cells and other tumor-reactive T cells results in the formation of tertiary lymphoid structures (TLS)." (PMID 38786066, 2024). "The subsequent single-cell and spatial analysis led to the discovery of cellular triads of CXCL13+ CD4+ T cells, DCs with maturation and regulatory molecules, and tumour-specific progenitor exhausted CD8+ T cells in the tumour of responders." (PMID 38760445, 2024). "Under the ambiance of HPV+ tumor cells, CD4+T cells manifested an upregulated expression of CXCL13 and IFNγ, indicating the enhanced differentiation toward CXCL13+ CD4+ T cells and TH1 phenotype." (PMID 39105803, 2024). "Recent work has shown that tumor-specific T cells can be found within the CD39+CD103+ subset, PD-1+CD8+ subset and CXCL13+CD8+ subset of T cells from patients with epithelial cancers." (PMID 38954022, 2024). "increased the expression of CCL19, CCL21, CXCL10, and CXCL13 through activation of the LT-α and LT-β pathways, promoting TLS formation, enhancing the local immune response, and delaying tumor growth." (PMID 39840050, 2024). "To further explore the function of human PD1+CXCL13+CD8+T cells in antitumor immunity in vivo, we established HNSCC subcutaneous tumor model by subcutaneously injected HNSCC cell line SAS into NCG mice." (PMID 39493749, 2024). "For example, CXCL13, a key chemokine involved in TLS development, is also expressed by tumor-infiltrating T cells outside TLSs7 or even tumor cells themselves." (PMID 38182879, 2024). "As a chemoattractant, CXCL13 facilitates the formation of TLS and plays an important role in anti-tumor activity through the CXCL13/CXCR5 axis and T follicular helper cells." (PMID 39544934, 2024). "In mouse models of pancreatic and ovarian cancer, the injection of CXCL13 induced TLS formation, enhancing the synergistic anti-tumor response of cellular and humoral immunity." (PMID 39840050, 2024). "Here, across multiple tumor types, we identify IFNβ-expressing CD4+ T cells that have a Ki67+CXCL13+ and a partial PD-1+ phenotype." (PMID 38383773, 2024). "After combination therapy, the CXCL13+ T cells in a patient with ATC had memory-like features, which were similar to those of tumor-reactive T lymphocytes from immunotherapy responders in other cancers." (PMID 38478516, 2024). "CD4.c16 and CD8.c11 both showed upregulation of CXCL13 in the MPR, which was in line with the indispensable role of CXCL13 in identifying tumor-reactive CD8+ expanding T-cell clones in multiple cancer types." (PMID 38343549, 2024). "While the HAS group was enriched in tumor cells and showed a lower infiltration of CD8-CCR7, CD8- CXCL13, CD8-GNLY, FCGR3A NK cells, XCL1 NK cells, plasma cell (PC) and other immune subsets." (PMID 39267750, 2024). "Tumors of CXCR2 KO mice had elevated CXCL13 levels to recruit B cells and B cell-derived CXCL11 in turn attracted CXCR3+ T cells into the tumor." (PMID 38786066, 2024). "This pattern was also observed for the TPK1 tumour cells and both CD4 + FOXP3 and CD8 + CXCL13 + ITGAE immune cells in the high-score group." (PMID 38730464, 2024). "Six tumor-infiltrating CD4+ T-cell clusters (CD4+_FOXP3, CD4+_CCR7, CD4+_LMNA, CD4+_ISG15, CD4+_CXCL13 and CD4+_MKI67) were identified after data filtering, integration, unsupervised clustering and annotation." (PMID 38383773, 2024). "Chaurio and colleagues identified that TLS formation was dependent on the CXCL13 pathway in CD4+ T cells, with blocking CXCL13 hindering TLS assembly and subsequently promoting tumor growth." (PMID 38111571, 2023).
tumor (continued). "In the tumor environment, TGF-ß acts as the major immunosuppressive cytokine and signals tumor progression, at the same time initiating CXCL13 expression in exhausted CD8+ T cells, synonymous for an escalation of the anti-tumor immune response." (PMID 36836910, 2023). "Focusing on ICI-responsive GCs, we found a substantial proportion of pre-treatment ISG-15+CD8+ T clonotypes in effector T-cell populations (CXCL13+CD8+ T, ZNF683+ Tem and GZMK+ Tem) of post-treatment EBV (+) tumours." (PMID 37735150, 2023). "The abundance of CXCL13-expressing (CD39+) CD8+ T cells and the expression of CXCL9 in the tumor microenvironment are robust predictors for ICB response in many different primary cancer types, including lung and triple-negative BC22–24,52." (PMID 37217652, 2023). "Higher expression of CXCL13 and HEYL in tumor cell than normal cell was found, as well as the lower expression of ANKRD35 and PDCD1LG2." (PMID 37397391, 2023). "Overall, our analyses illustrate ICI-mediated release of T cell checkpoint engagement of tumor-specific, PD1+ TOX+ CD8 T cells upregulates CXCL13, which subsequently recruits CXCR5+ B cells and Tfh to form TLS in the TME." (PMID 37435085, 2023). "Several recent studies demonstrate that human CXCL13+CD4+ and CXCL13+CD8+ T cells, which are also phenotypically similar to exhausted or hyperactivated T cells, are tumor antigen–specific and mediate responses to the anti-PD-1 therapy." (PMID 37546701, 2023). "This indicated a relatively higher tumor reactivity in MSI CD8+ T cells, as documented recently for CXCL13+CD8+ T cells in MSI CRC1." (PMID 37968259, 2023). "Thus, intratumoral CXCL13+ T cells are indicative of existing anti-tumour immunity and predictive of a positive response to immunotherapy which, in addition to direct tumour cell killing, may derive from their potential to facilitate TLS formation and B cell recruitment." (PMID 37520560, 2023). "CD20 is expressed on both anti-tumor B cells and tBregs, and targeting CD20 B cells with CXCL13-coupled CpG-ODN can enrich and inactivate tBregs, thereby controlling tumor immune escape." (PMID 37342327, 2023). "In contrast, CXCL13 blockade abrogated TLS formation in intraperitoneal tumor-bearing mice, increasing tumor growth." (PMID 38023214, 2023). "High CXCL13 levels, in turn, lead to the recruitment of CXCR5-positive Tfh and B cells to, and their aggregation in, the tumor site." (PMID 36836910, 2023). "Some of the upregulated genes such as CXCL13 and CXCL11 and KLK5 have been experimentally verified in prior studies to regulate humoral immune response and support tumor infiltration." (PMID 37697300, 2023). "In the Non-Small Cell Lung Cancer (NSCLC) group, CXCL13 expression levels increased with later TNM staging and poorer tumor differentiation." (PMID 37025603, 2023). "Abnormal activation of Tfh cells and B cells mediated by CXCL13 and IL21 has been observed in tumor tissues." (PMID 37638029, 2023). "The abundance of CXCL13+ CD4+ T cells, the tumor antigen‐specific T cells to immune‐checkpoint blockade, was significantly higher in primary tumors, and a subset of CD4+ T cells had high expression levels of several cytotoxic genes, including GZMB and GZMK." (PMID 37743226, 2023). "Measuring the abundance of CXCL13+ CD8+ and CXCL13+ CD4+ T cells together in tumor samples is a powerful biomarker of response to ICB in multiple cohorts, with higher predictive accuracy than TMB." (PMID 38066642, 2023). "In groups A5, A6, A7, and A8, genes such as CXCL13, HSPA1A, CREM, CCL4, and FOS were highly expressed in CD8+ or CD4+ T cells in tumor tissues." (PMID 37762493, 2023). "Cytokine-based signalling pathways, such as the CXCL13/CXCR5 axis and the CCL19,21/CCR7 axis, mediate the recruitment of B cells and TLSs in tumours." (PMID 36890557, 2023). "In their study, worse tumor features and poor overall survival in patients with CRC were influenced by CXCL1, CXCL2, CXCL8 and CXCL13, which contributed to CRC treatments." (PMID 37393391, 2023).
tumor (continued). "Results showed that the expression level of genes including MORF4L2, CTSL1, WIPF1, CXCL13, C5orf15, LIPA, and ISG20 significantly elevated in tumor tissues." (PMID 36639648, 2023). "To achieve this, we analyzed the expression levels of CXCL13 and compared them to the TNM staging and tumor differentiation of each patient." (PMID 37025603, 2023). "CXCL13, IL36γ, and CCL27 expression in the G4 tumor was higher than in the normal brain and other MB subgroups." (PMID 35563678, 2022). "In the CXCL13-treated group, the infiltration of CD8+ T cells around the TLS was clearly increased, and the survival time of tumor-bearing mice was also prolonged." (PMID 35552285, 2022). "As with recent studies, CXCL13/CD163 double staining results confirmed that CXCL13 is secreted by a variety of cells within the TME, including tumor cells and tumor-infiltrating immune cells." (PMID 35570844, 2022). "CXCL13 and the receptor CXCR5 represent an emerging example of a chemokine signaling axis that demonstrates the ability to regulate tumor growth and progression." (PMID 35770088, 2022). "The CXCL13/CXCR5 axis is activated by the interaction of B cells and Tfh cells to accelerate the GC reaction; it participates in the migration of tumor B cells and Tfh cells in the TME." (PMID 34689225, 2022). "Drebrin1-expressing cells were most prominently represented in the exhausted tumor-infiltrating CD8+ T cell clusters at the single-cell level, although CXCL13 was expressed in the exhausted tumor-infiltrating CD4+ and CD8+ T cell clusters." (PMID 36430217, 2022). "Moreover, we analyzed the correlation between CXCL13 expression and clinicopathological characteristics, prognosis, Mismatch Repair Genes (MMRs), Microsatellite Instability (MSI), tumor mutation burden (TMB), immune cells infiltration, immune-related genes, and the role in tumor immunotherapy." (PMID 35141160, 2022). "When the cancer microenvironment is enriched in CXCL13, the recruitment of CXCR5-expressing leukocytes to the tumor microenvironment increases." (PMID 35053457, 2022). "We found that 47 genes were upregulated in tumor tissues compared to normal tissues, such as CD48, TIGIT, GNLY, CCL19, CCL5, CXCL13, CCL17 and NKG7." (PMID 36713530, 2022). "Since tumor-reactive CD4+ and CD8+ T cells both secrete CXCL13, it is likely that this chemokine plays a key role in controlling the recruitment of immune cells to the TME as well as in the spatial organization of the immune cell infiltrate within the tumor." (PMID 35439168, 2022). "By GSEA enrichment analysis of normal and tumor tissues, we found that CXCL13 functions and pathways in normal tissues may be mainly related to metabolism and some basic immune functions, while in tumor tissues, CXCL13 was related to tumor-related pathways and functions." (PMID 35141160, 2022). "The levels of CXCL13, ICAM-1, MCP-5, and IL-7 in the serum, and the levels of IL-15 and sFasL in the tumor tissue decreased significantly after rAd-mIL-28B treatment relative to rAd-EGFP." (PMID 35935577, 2022). "The expressions of serum CXCL13, ICAM-1, MCP-5, IL-7, and TNF-α in tumor-bearing mice treated with rAd-mIL-28B were lower compared to rAd-EGFP-treated mice (P < 0.05)." (PMID 35935577, 2022). "Probably due to advances in analytical techniques, however, the expression of CXCL13 has been reported in CD4+ T cells present during aging and in tumor TLSs." (PMID 35880181, 2022). "In CXCL13/CD163 double staining, CXCL13 was stained red in the cytoplasm of both tumor cells and TAMs, whereas CD163 was visible in brown plasma membrane staining of M2 macrophages." (PMID 35570844, 2022). "In our study, CXCL13/CXCR5 axis interacts with PD-1/PD-L1 inhibitory signal and acts a double-edged sword in tumor progression and response to immunotherapy." (PMID 35392977, 2022).
tumor (continued). "Most TSGs including the essential chemokines for the formation of TLSs such as CXCL13 and CCL21 showed greater frequency of CNV gain, which indicated the neogenesis of TLSs in tumor tissue." (PMID 36420257, 2022). "Furthermore, CCR5-CCL4/CCL5 and CXCR3- CXCL9/CXCL10/CXCL11/CXCL13 axis were significantly correlated with CD 4 T and CD 8 T cells, indicating that these interactions may be essential for the recruitment of the T lymphocytes into tumor." (PMID 35530341, 2022). "This review discusses how CXCL13/CXCR5 signaling modulates cancer and immune cells to promote lymphocyte infiltration, activation by tumor antigens, and differentiation to increase the antitumor immune response." (PMID 35053457, 2022). "The tumor stains for one or more of the FDC markers including CD21, CD23, CD35, D2-40, clusterin, CXCL13, FDC-secreted protein and Serglycin." (PMID 35941667, 2022). "• A functional antitumor response, intra-tumor cell retention (ITGAE, ITGA1, etc.) and tumor residency (ALOX5AP, CXCL13, etc.) similar to CD39+CD8+T cells.• Expressed activation/co-stimulation genes to resist exhaustion." (PMID 36451828, 2022). "Especially, the combination of tumor intrinsic factors, like TMB, and genes representative of immune infiltration in the TME, like TIS or CXCL13, show promise in exploratory studies." (PMID 35174087, 2022). "Due to their close relationship with CXCL13, FDCs appear to play an important role in modifying the immune environment, particularly THFs, during the HPV+ HNSC tumor immunity process." (PMID 36291667, 2022). "Because the CXCL13/CXCR5 axis can orchestrate the immunological dynamics in the TME, it would be interesting to investigate the involvement of miR-934–mediated tumor-macrophage crosstalk in the systemic metastasis of other cancer types." (PMID 36248881, 2022). "Based on the promising findings on the prognostic relevance of baseline CXCL13 serum levels, we subsequently evaluated the potential regulation of CXCL1, CXCL10 and CXCL13 after tumor resection." (PMID 36077611, 2022). "T cells secrete CXCL13 to recruit CXCR5+ immune cells to the TME, thus initiating jointly anti-tumor immune responses." (PMID 35392977, 2022). "In the TLS region, CXCL13 was highly coexpressed with CD4+ T cells, whereas CD8+ T cells predominantly expressed CXCL13 in the tumor and stromal regions." (PMID 35552285, 2022). "In addition, our study revealed that MXRA8 expression correlated with the expression of multiple metastasis-associated chemokines (CXCL12, CXCL13, CCL9, CCL21, CXCR4, CXCR5, and CCR7), suggesting that MXRA8 may be involved in tumor invasion and metastasis by regulating the secretion of chemokines." (PMID 36703779, 2022). "CXCL13 potentially promotes TLS formation and is correlated with B cell infiltration and germinal center maturation at the tumor site." (PMID 35563678, 2022). "Moreover, although MTAP/CDKN2AMUT RCC may be insensitive to targeted therapy, the high degree of tumor heterogeneity and higher PD-L1 and CXCL13 expression characterizations reflected that MTAP/CDKN2A-deficient features could benefit from immunotherapy for patients with RCC." (PMID 35979371, 2022). "To identify cells producing CXCL13 involved in TLS formation, we performed RNA ISH double staining (CXCL13 and CD4+ T cells, CXCL13 and CD8+ T cells) using HGSC tumor specimens." (PMID 35552285, 2022). "Cluster 2 expressed a higher level of interferon-gamma (IFN-γ) than did the other CD4+CXCL13+ clusters, indicating that this type of CD4 T cells has a potential role in killing tumor cells." (PMID 36357424, 2022). "As for skin LC, a significant production of APRIL, IL-18 and CXCL13 was markedly increased in the presence of Tfh and B cells." (PMID 34324611, 2021). "High expression of exhausted T-cell marker genes supported by established studies, including CXCL13, HAVCR2, and PDCD1, was concentrated in tumor tissue in single-cell transcriptional profiles." (PMID 34434188, 2021).
tumor (continued). "Pan-cancer expression analysis results showed that ITLN1, TSPAN11, CXCL13, and GPRC5B were downregulated and TIMP1 was upregulated in most tumor samples, including COAD, which was consistent with the results of the TCGA and GEO cohorts." (PMID 33579281, 2021). "Furthermore, to explore whether CXCL13 can mediate long-term protection against primary tumors, 4T1-CXCL13-1 (n = 3) and 4T1-CXCL13-2 (n = 9) mice were rechallenged with parental 4T1 cells after over 6 months of complete tumor regression." (PMID 35693216, 2021). "Four tumor microenvironment-related genes (CD79A, CXCL13, IL6 and CCL19) were identified as biomarkers for PRCC prognosis." (PMID 33993869, 2021). "Another study demonstrated that CXCL13, which is regulated by interferon regulatory factor 5 (IRF5), mediates CXCR5+ B cells and T cells homing to tumors, thereby eliciting an anti-tumor immune response." (PMID 34947813, 2021). "Past studies showed that CXCL13, IDO1, PI3, SPP1 and TRIM22 were closely correlated with the prognosis, immunization and chemotherapy sensitivity of tumor." (PMID 34736480, 2021). "As expected, we also saw CXCL1, CXCL8, CXCL10, CXCL11, CXCL13, and CXCL14 in tumor tissues were upregulated in the results of TCGA data and the difference was statistically significant (p < 0.05)." (PMID 34794429, 2021). "Tumor immune infiltration analysis results showed that TSPAN11, GPRC5B, TIMP1, and CXCL13 protein levels were significantly positively correlated with CD4+ T cells, macrophages, neutrophils, and dendritic cells." (PMID 33579281, 2021). "Among CD4+ T cells, naïve CD4+ T, CXCL13+/CD4+ Th, and CD4+ T‐reg cells showed anti‐immunological activity and predominantly inhabited in tumor tissues, suggesting an immunosuppressive environment." (PMID 34185421, 2021). "The roles of the CXCL13/CXCR5 axis participating in the malignant tumors are context-dependent, including pro-tumor and anti-tumor activities." (PMID 34947813, 2021). "The CXCL13/CXCR5 axis plays multifaceted roles in intracellular signaling transduction pathways and interactions among tumor cells, stromal cells, and lymphocytes." (PMID 34947813, 2021). "CXCL13, also secreted by stromal cells, upregulates the expression of RANKL on stromal cells, promoting tumor cell migration and lymph node metastasis via the RANK-RANKL pathway." (PMID 34947813, 2021). "Compared with the paracancerous tissues, the expression of CXCL13(P = 0.0093), IDO1(P = 0.0068), PI3(P = 0.0161), SPP1(P = 0.0122) in tumor tissues was significantly increased, while TRIM22(P = 0.0342) was significantly decreased." (PMID 34736480, 2021). "This group performed deep transcriptome sequencing with a single-cell RNA of tumor infiltrating CD8+ T cells reactive to a clonal cancer neoantigen (MTFR2) in a NSCLC patient and found that CXCL13 was upregulated." (PMID 34572771, 2021). "Previous studies also demonstrated that TFH cells release CXCL13 to recruit B cells into TLS35, which then present tumor antigens to T cells." (PMID 34663810, 2021). "For example, tumor-infiltrating Tregs (C08_CD4.CTLA4, C10_CD4.CXCL13) and exhausted T cells (C04_CD8.LAYN) clustered together, demonstrating a huge difference between these cells and others." (PMID 33674641, 2021). "Consistent with all above the results, immune-related genes were highly expressed in hot tumor, for instance, CXCL9, TCL1A, CCL19, CXCL13, MS4A1, and C4orf7." (PMID 33816503, 2021). "CXCL13 is secreted by multiple populations of cells within the TME, including stromal cells, endothelial cells, lymphocytes, and tumor cells." (PMID 34947813, 2021). "Flow cytometry showed that the ratios of tumor-infiltrating CD4+ and CD8+ T lymphocytes were significantly elevated in the CXCL13-overexpressing tumor, compared with parental 4T1 and 4T1-pCDH." (PMID 35693216, 2021).